IL6 (interleukin 6)
Diseases named in the same sentence as IL6 in open-access papers (continued):
Sharing a sentence is not in itself a finding about the gene and the disease.
heart failure (continued). "In the same way, the increased IL-6 expression by cardiac tissue has been associated with the progression of heart failure." (PMID 32455143, 2020). "In our study, RosA inhibited the increase of pro-BNP and IL-6 induced by Dox, which suggests that RosA has protective ability against the heart failure caused by Dox." (PMID 32075047, 2020). "Elevated IL-6 is associated with higher risk of left ventricular dysfunction and progression to heart failure in humans, and hypertrophy in rodents." (PMID 32973791, 2020). "Heart histological staining and mRNA levels of genes associated with heart failure (Acta1 and Nppa), inflammation (IL‐6), and fibrosis (Ctgf, Col1a2, Timp1, and Mmp9) were assessed." (PMID 32133617, 2020). "IL-6 has been shown to have cardioprotective effects, but chronic or excessive expression of IL-6 can be fatal and has been shown to cause heart failure in a rodent model." (PMID 31871429, 2019). "They found an association between IL-6 concentrations and the extent of asymptomatic LV systolic dysfunction, and its diagnostic value in predicting progression to heart failure during follow-up." (PMID 31739518, 2019). "Clinical studies have shown that circulating IL-6 is not only elevated in patients with periodontitis, but also in patients with heart failure—a major risk factor for AF (see review by Wollert and Drexler)." (PMID 30071583, 2018). "Persistent inflammation, with chronically elevated concentrations of proinflammatory cytokines like TNF-α, ET-1, and IL-6, plays a pathogenic role in heart failure." (PMID 29093735, 2017). "These cytokines are also closely linked to the genesis of cancers (IL-6), to cardiac remodeling in heart failure and to the risk of community-acquired pneumonia requiring hospitalization (both IL-6 and TNF)." (PMID 28174512, 2017). "Increased levels of cytokines, especially IL-6 and tumor necrosis factor alpha (TNFα), are also associated with frailty, decreased muscle endurance, and heart failure." (PMID 27148509, 2016). "IL-6 is known to be elevated systemically in heart failure and levels have been associated with severity of disease." (PMID 27884156, 2016). "IL-6 is an inflammation-associated gene elevated in pathological hypertrophy, and the elevation of IL-6 has been linked to the development of heart failure." (PMID 25136830, 2014). "In the Framingham Heart Study, increased inflammatory markers, such as CRP, interleukin-6 and TNFα levels, were able to identify asymptomatic older subjects in the community who were at high risk for the future development of heart failure." (PMID 25142635, 2014). "Prolonged chronic high levels of IL-6 after MI are considered as a cause of hypertrophy and heart failure." (PMID 23406316, 2013). "Elevated IL-6 level is associated with heart failure and is strongly prognostic of 1-year mortality." (PMID 22574112, 2012). "Elevated intracardiac interleukin-6 (IL-6) is reported and causes cardiac hypertrophy through the IL-6 signal transducing receptor component, glycoprotein 130 (gp130), which eventually leads to heart failure (HF)." (PMID 21792366, 2011). "Inflammation plays a pivotal role in the development of heart failure, potentially contributing differently to its various subtypes, with evidence highlighting a specific association between the interleukin-6 (IL-6)/C-reactive protein (CRP) pathway and the pathogenesis of HFpEF." (PMID 41169425, 2025). "It has been reported that p38 activation has a apoptotic and profibrotic effect by inducing apoptosis and the release of TNF-α and IL-6 in cardiomyocytes, which are closely associated with the development of fibrosis, adverse cardiac remodeling, and heart failure." (PMID 40610735, 2025). "We hypothesised that preoperative interleukin 6 (IL-6) is associated with postoperative biomarker release indicative of myocardial injury and heart failure." (PMID 40491666, 2025).
heart failure (continued). "We assessed relationships between interleukin-6 (IL-6) tertiles (T1-3) and all-cause death, cardiovascular death, and subsequent heart failure hospitalization (sHFH) in 286 patients recently hospitalized with heart failure with preserved ejection fraction." (PMID 36896709, 2023). "IL-6, a pro-inflammatory cytokine produced by both cardiomyocytes and fibroblasts, is increased in post-MI patients and elevated in patients with heart failure, where it correlates with increased risk of cardiovascular events and ventricular dysfunction." (PMID 37668685, 2023). "Furthermore, previous studies have shown that RDW is associated with the levels of interleukin 6 in heart failure and tumor necrosis factor in coronary artery lesions of Kawasaki disease." (PMID 36920980, 2023). "Indeed, each 1-unit log increase in IL-6 was associated with a 24% increased risk of subsequent heart failure hospitalization." (PMID 36896709, 2023). "We examined whether circulating levels of interleukin-6 identify patients at greater risk of adverse outcomes following hospitalization with heart failure with preserved ejection fraction." (PMID 36896709, 2023). "Other authors showed that the level of nervonic acid is inversely correlated with LDL-C, HDL-C and directly associated with heart failure, cardiovascular risk, cardiovascular and all-cause mortality, markers of inflammation and endothelial activation (hsCRP, IL-6, ICAM-1)." (PMID 36140306, 2022). "Association between IL-1 and IL-6 signaling with heart failure risk estimated in MR analysis." (PMID 34881299, 2021). "In addition, T cell-transferred NSG-DR1 mice displayed an increased myocardial Il6 expression, a proinflammatory cytokine associated with left ventricular dysfunction and a heart failure predictor in humans." (PMID 33679735, 2021). "Furthermore, some studies have demonstrated an independent association between higher IL-6 and younger age in patients with heart failure." (PMID 33535417, 2021). "Myocardial induction of IL‐6 is closely associated with the progression of heart failure." (PMID 32302067, 2020). "Chronic IL-6 signaling activation in heart underlies the pathogenetic link between inflammation and LV dysfunction, which leads to reduced contractility and contributes to the progression of compensatory LV hypertrophy to heart failure." (PMID 31739518, 2019). "Elevated IL-6 level is associated with heart failure and is a strong predictor of 1-year mortality." (PMID 29674727, 2018). "Thus, the only biomarker that exhibited a statistically significant association with 60 day death or heart failure re‐hospitalization was IL‐6 using the age‐adjusted model." (PMID 29650706, 2018). "Additionally, higher plasma levels of TNF-α and IL-6 have been shown to be associated with LV dysfunction in patients with heart failure." (PMID 27977796, 2016). "Our hypothesis is also supported by the finding that after AMI, increased circulating IL-6 concentrations at baseline and after hospital discharge were associated with heart failure and impaired LV ejection fraction." (PMID 25100442, 2014). "Among the several potential causes of this association, inflammatory cytokines as TNF-α as well as IL-6 have been shown to be predictors in heart failure; these cytokines may impact bone marrow function and iron metabolism." (PMID 24660068, 2014). "Given the established role of cytokines such as interleukin-1, interleukin-6, and tumor necrosis factor alpha in the pathophysiology of heart failure, it is plausible that the symptomatic relief associated with MSCs may be, at least partly, secondary to their immunomodulatory capacity." (PMID 40422568, 2025). "Similarly, interleukin-6 is known to be associated with the progression of heart failure." (PMID 37445494, 2023). "In advanced heart failure, elevated IL-6 levels have been correlated with symptom severity, suggesting a role in the pathogenesis of remodeling." (PMID 41590667, 2026).
heart failure (continued). "Compared with heart failure-associated transudative ascites, malignant ascites demonstrated higher levels of TNF-α, IL-6, IL-10, IL-12p70, IL-18, IL-23, s4-1BB, and TGF-β1, while albumin levels were lower." (PMID 42193466, 2026). "Serum IL-6 is found to correlate inversely with left atrial strain in patients with persistent AF and heart failure." (PMID 41590667, 2026). "Heart failure (HF) is frequently marked by persistent inflammation, characterized by increased levels of pro-inflammatory cytokines such as interleukin-6 (IL-6), interleukin-1b (IL-1b), and tumor necrosis factor alpha (TNF-a) in the blood of HF patients." (PMID 39736852, 2025). "Since then, multiple studies have emphasized the prognostic relevance of inflammatory markers such as C-reactive protein (CRP), tumor necrosis factor-alpha (TNF-α), and interleukin-6 (IL-6) in heart failure." (PMID 40869365, 2025). "In our cohort, elevated IL-6 levels were associated with NT-proBNP and left ventricular hypertrophy, in agreement with prior studies linking IL-6 to myocardial fibrosis, heart failure progression, and mortality." (PMID 41450363, 2025). "A systematic review and meta-analysis reported that omega-3 supplementation significantly lowered TNF-α and IL-6 levels in patients with heart failure, suggesting a potential role in controlling cardiovascular inflammation." (PMID 40427653, 2025). "Our results suggest that the elevated levels of IL-6 are due to chronic inflammation that will eventually lead to heart failure." (PMID 40643523, 2025). "A recently published study using data from the LURIC study that examined IL-6 and hsCRP in patients with heart failure also found IL-6 to be the superior marker." (PMID 40806466, 2025). "In heart failure where there is pressure overload, the induction of IL-6 is accompanied by an upregulation of the IL-6 receptor (IL-6Rα)." (PMID 40360833, 2025). "Although extensive research has focused on IL-6 in cardiovascular diseases, heart failure, and valvular disease, its role in HCM remains largely unexplored." (PMID 40535153, 2025). "Proteins that were selected by Lasso regression for each outcome that commonly included GDF15 and IL6, significantly improved the prediction of mortality, mobility limitation, and heart failure compared with age, sex, and race alone." (PMID 39695064, 2025). "During the progression of heart failure, negative regulatory mechanisms be activated to limit the expression of IL-6 and other pro-inflammatory cytokines." (PMID 40360833, 2025). "Anakinra attenuates systemic inflammation with signals for heart failure prevention, whereas ziltivekimab drives marked reductions in hsCRP and IL-6 and is advancing in phase 3." (PMID 41302946, 2025). "CXCR4 plays a crucial role in promoting inflammatory responses and tissue remodeling, while IL-1 and IL-6 are pro-inflammatory cytokines involved in the progression of myocardial injury and heart failure." (PMID 40427493, 2025). "Since 1990, studies have confirmed elevated levels of various inflammatory mediators, including TNF-α, IL-6, IL-1β, IL-18, and immune antigens, in the plasma of heart failure patients." (PMID 40671145, 2025). "The proinflammatory response is a hallmark of heart failure, and the overproduction of inflammatory factors (e.g., TNF-α and interleukin-6 (IL-6)) can induce mitochondrial DNA damage, inhibit antioxidant factors and promote ROS generation." (PMID 40507126, 2025). "A direct correlation of IL-6 level and severity of cardiac dysfunction has been reported in heart failure patients." (PMID 41293249, 2025). "Studies have confirmed that IL-6 is positively correlated with the severity of heart failure, and chronic renal insufficiency can increase the level of serum IL-6 in patients with heart failure." (PMID 40837364, 2025). "Our recent meta-analysis also confirmed the reduction in tumor necrosis factor-α and interleukin-6 in patients with heart failure, after n-3 PUFA ingestion." (PMID 38777807, 2025).
heart failure (continued). "Infusion of IL-6 induced diastolic dysfunction in rats, which is clinically referred to as heart failure with preserved ejection fraction (HFpEF)." (PMID 38256155, 2024). "Heart explant specimens from patients with advanced heart failure had higher IL-6 and IL-6R transcript levels than controls, and IL-6 levels were inversely correlated with left ventricular ejection fraction." (PMID 38256155, 2024). "Among these, 2 lipid mediators showed a possible increase during acute kidney injury or (right) heart failure respectively, while the established inflammation parameters such as IL-6 only showed a congruency to a low degree with 11 other lipid mediators." (PMID 39959584, 2024). "IL-10 can also reduce proinflammatory cytokines such as TNF-α, IL-1β, and IL-6, as well as cardiac contractility in heart failure." (PMID 39200761, 2024). "Following immune dysregulation in heart failure, inflammatory cells in the body release inflammatory cytokines (such as TNF-α, IL-6, NF-κB), which drive the progression and worsening of heart failure." (PMID 39199348, 2024). "In this context, serum levels of cytokines, including interleukin (IL)-1β and tumor necrosis factor-alpha (TNF-α), and IL-6 are elevated in HD patients, suggesting an adverse role of these substances in the pathogenesis of cardiac failure in these patients." (PMID 39070454, 2024). "Research has demonstrated that in rat models of heart failure induced by the ligation of the left anterior descending coronary artery, ischemia and hypoxia trigger the production of IL-6." (PMID 39432214, 2024). "There is increasing evidence that IL-6 plays a role in the development of cardiovascular diseases and can be used as a biomarker in heart failure." (PMID 38393459, 2024). "For the biomarker interleukin-6, five studies were eligible that analyzed the correlation between IL-6 and heart failure." (PMID 38397422, 2024). "Physical exercise training in patients with heart failure was reported to reduce IL-6 and TNFα levels and improve functional status." (PMID 38256155, 2024). "We sought to investigate metabolomic profiles and temporal changes in IL6, Ang-2, and markers of glycocalyx perturbation from admission to discharge in eighteen patients with heart failure complicated by CS (HF-CS)." (PMID 38139435, 2023). "Cytokines, TNF-α, IL-1β, and IL-6, were found to be elevated in patients with heart failure, and their higher levels appear to be directly related to LVEF dysfunction." (PMID 35997998, 2023). "Second, in line with the recent insights from CANVAS, the study identifies Interleukin-6 as a potential biomarker in the evaluation of therapeutic measures in heart failure." (PMID 37445494, 2023). "Excessive IL-6 production also contributes to excessive LV remodeling and heart failure in patients with STEMI." (PMID 37859889, 2023). "Elevated levels of IL-6 or TNF are associated with an increased risk of cardiovascular events and a worse prognosis in patients with heart failure." (PMID 37047011, 2023). "For several years, it has been known that the expression of interleukin-6 is increased in the circulation and myocardium of patients with heart failure." (PMID 37445494, 2023). "The contribution of inflammatory mediators such as tumor necrosis factor-α, interleukin-6, monocyte chemoattractant protein-1, nuclear factor kappa B, and oxidative injury in heart failure, which also leads to renal damage." (PMID 37691634, 2023). "CRS is the most common adverse event following CAR-T cell therapy and is caused by the release of large amounts of inflammatory factors (IL-6, IL-1, GM-CSF, etc.), which can lead to fever and, in severe cases, heart failure and death." (PMID 38187386, 2023). "Tumor necrosis factor (TNF) and IL-6 are well known serum biomarkers of heart failure, along with IL-1β, but IL-1β is better as a tissue biomarker rather than a serum biomarker, as its sera levels are low." (PMID 36937911, 2023).
heart failure (continued). "Interleukins, specifically interleukin-1 (IL-1) and interleukin-6 (IL-6), play a crucial role as mediators of the inflammatory response in cases of heart failure." (PMID 37664375, 2023). "In a recent clinical study, IL-6 has been proposed as a potential therapeutic target in specific heart failure subpopulations." (PMID 37175685, 2023). "Acute release of Interleukin-1 (IL1), IL6 and plasminogen activator inhibitor 1 (PAI-1) have been related to elevating risk of heart failure." (PMID 36128671, 2022). "IL-6 is a pleiotropic pro-inflammatory cytokine that plays an important role in the progression of heart failure." (PMID 36362245, 2022). "In cardiovascular diseases, the production of various inflammatory cytokines, including TNF-α, IL-1β, and IL-6, leads to tissue damage, promoting atherosclerotic plaque formation, reduced vascular function, and progression of heart failure." (PMID 35431967, 2022). "Evidence from prior research suggests that TNF-α and IL-6 levels serve as predictors of death in heart failure patients." (PMID 36547425, 2022). "CRP and IL-6 are common inflammatory mediators that are mainly produced by activated macrophages, whereas galectin-3 is a newly discovered inflammatory marker of heart failure and is produced by macrophages." (PMID 35356068, 2022). "Nevertheless, Il-6, which is a proinflammatory cytokine, was found to be elevated in patients with heart failure." (PMID 35682939, 2022). "Raloxifene attenuates cardiac remodeling and inflammation induced by pressure overload, and oxidative stress in heart failure by inhibiting IL-6/STAT3." (PMID 35812340, 2022). "Compared to the no-AF group, new-onset AF patients were older with a positive history of chronic kidney disease and heart failure, had higher IL-6, creatinine and urea serum levels whereas their platelet count was reduced." (PMID 35454369, 2022). "It has been indicated that acute release of IL1, IL6 and plasminogen activator inhibitor 1 (PAI-1) were related to elevating risk of heart failure." (PMID 36128671, 2022). "In patient with heart failure, both the percentage of human leukocyte MDSCs in the blood and plasma level of IL-6, IL-10 were significantly increased." (PMID 36263056, 2022). "Some research reports that some proinflammatory cytokines, including TNF-α and interleukin-6 are increased in hypertensive patients with heart failure." (PMID 35721105, 2022). "In a large cohort of patients with heart failure, elevated IL-6 levels were found in over 50% of patients and were associated with reduced left ventricular ejection fraction (LVEF) and poor clinical outcomes." (PMID 36269647, 2022). "IL-6 is a multifunctional cytokine that is an important biomarker that predicts the severity, prognosis, and mortality of heart failure." (PMID 35242825, 2022). "Elevated IL-6 and TNF-α in plasma were associated with disease severity of HCM and even heart failure with preserved ejection fraction (HFpEF)." (PMID 36267414, 2022). "Activations of the Jak/STAT pathway are often considered part of the IL-6 cascade, neglecting the involvement of other IL-6 family members in the development of heart failure." (PMID 35163735, 2022). "The pro-inflammatory cytokines TNFα, IL-1β and IL-6 are all involved in the inflammatory response related to the pathogenesis of heart failure." (PMID 36278179, 2022). "TNF-α also induces the release of IL-6, which is implicated in the pathophysiology of cardiac cachexia via the induction of an acute phase response and is supported by high circulating levels of IL-6 in heart failure patients." (PMID 35326441, 2022).